CLDN7 (claudin 7)
Diseases named in the same sentence as CLDN7 in open-access papers (continued):
Sharing a sentence is not in itself a finding about the gene and the disease.
breast tumors (4 papers, 2005 to 2017). "We tested this profile (TN and low expression of at least two of four epithelial cell-cell adhesion markers; claudin 3, claudin 4, claudin 7 and E-cadherin) in a large cohort of breast tumors with long-term follow up." (PMID 28045912, 2017). "This cluster had low expression of the claudin genes CLDN3, CLDN4, and CLDN7, raising the possibility that tumors in this cluster were members of the claudin-low subtype, a group of breast tumors known for their invasive, mesenchymal-like behavior." (PMID 23667446, 2013). "Claudin 7 expression was inversely correlated with histological grade in a large series of breast tumors." (PMID 15743505, 2005). "One member of this family, claudin 7, has been shown to be expressed in the human mammary epithelium and some breast tumors." (PMID 15743505, 2005).
metastatic disease (4 papers, 2011 to 2023). "Examination of differential protein expression between the glandular primary tumor organoid partial EMT sublines revealed no major differences in protein expression, whereas the glandular metastatic tumor organoid had reduced Cldn7 compared to the glandular primary tumor organoids." (PMID 36828915, 2023). "Moreover, in 144 RCC patients from Peking University First Hospital, immunostaining results confirmed that ccRCC patients with low CLDN7 protein expression levels experienced recurrent or metastatic tumors earlier after surgery, compared to those with higher expression levels." (PMID 30428910, 2018).
oncocytoma (4 papers, 2010 to 2025). "Previous gene expression microarray analysis revealed that Claudin-7 was overexpressed in CHRCC versus oncocytoma and other tumor subtypes." (PMID 31737127, 2019). "Using microarray analysis of renal tumours, claudin-7 mRNA, a distal nephron marker, was overexpressed in chRCC compared with that in oncocytoma, ccRCC, and pRCC." (PMID 29208006, 2017). "Further immunohistochemical analysis of two independent cohorts showed that claudin-7 expression was detected in 67 and 100% of chRCCs, 0 and 7% of ccRCCs, 28 and 90% of pRCCs, and 26 and 45% of oncocytomas." (PMID 29208006, 2017). "The distal nephron proteins claudin-7 and claudin-8 have potential use as immunohistochemical biomarkers in the differential diagnosis of chromophobe renal cell carcinoma and oncocytoma." (PMID 20205900, 2010).
pancreatic adenocarcinoma (4 papers, 2017 to 2020). "CLDN7 palmitoylation can promote cell invasion by association with uPAR, MMP14 and CD147, and also play a role in epithelial-mesenchymal transition (EMT) of pancreatic adenocarcinoma cells." (PMID 28055967, 2017). "In contrast to ours and these other previously published results, co-expression of EpCAM and Claudin-7 in human embryonic kidney (HEK) cells and in rat pancreatic adenocarcinoma (AS) cells increases ERK activity and cell migration." (PMID 30304739, 2018).
renal carcinoma (4 papers, 2011 to 2025). A carcinoma arising from the epithelium of the renal parenchyma or the renal pelvis. "In renal cancer, CLDN7’s downregulation due to promotor hypermethylation is associated with poor prognosis." (PMID 41188181, 2025). "Finally, we identify early dysregulated genes (e.g., FBP1, CCDC8, ECHS1, CLDN7) and pathways in renal cancer, often related to metabolism (e.g., pentose phosphate pathway)." (PMID 41188181, 2025).
chromophobe renal cell carcinoma (3 papers, 2010 to 2024). Chromophobe renal cell carcinoma is a rare subtype of renal cell carcinoma, originating from the intercalating cells of the collecting ducts and macroscopically manifesting as a well-circumscribed, highly lobulated, solid tumor that is usually diagnosed at an early stage. "We have 10 years of experience with the combined immunohistochemistry for the “three 7” markers, that is, CK7, CD117, and Claudin-7, to diagnose chromophobe renal cell carcinoma and exclude the mimics." (PMID 31737127, 2019). "This study is aimed at evaluating the clinical usefulness of the combined immunochemistry for the “three 7” markers (CK7, CD117, and Claudin-7) to distinguish chromophobe renal cell carcinoma from these mimics." (PMID 31737127, 2019).
congenital tufting enteropathy (3 papers, 2018 to 2023). "Conversely, mutations in human SPINT2 were associated with congenital tufting enteropathy characterized by severe intestinal dysfunction with induced EpCAM cleavage and decreased claudin-7 expression that resulted in organoid rupture." (PMID 37830556, 2023). "Loss of EpCAM causes loss of Claudin-7 from the intestinal epithelium which is associated with congenital tufting enteropathy and loss of intestinal epithelial integrity in mice and humans." (PMID 30304739, 2018). "In humans, mutations in EpCAM cause congenital tufting enteropathy (CTE), a disease which is associated with loss of tight junction protein Claudin-7 and increased actomyosin contractility at epithelial cell-cell junctions leading to the disruption of intestinal epithelial integrity." (PMID 30304739, 2018).
dysplasia (3 papers, 2011 to 2023). A usually neoplastic transformation of the cell, associated with altered architectural tissue patterns. "In the present study, we investigated the levels of claudin-7 mRNA during colorectal carcinogenesis and found that claudin-7 mRNA is significantly decreased in mild/moderate dysplasia, severe dysplasia and carcinomatous tissue." (PMID 21310043, 2011). "In general, our analysis showed that the claudin-7 mRNA levels were decreased as an early event in the carcinogenesis, as the claudin-7 mRNA level is decreased already in the mild/moderate dysplasias." (PMID 21310043, 2011). "The levels of claudin-7 mRNA in normal mucosa from individuals with dysplasia or carcinomas were not affected." (PMID 21310043, 2011).
endometrioid adenocarcinoma (3 papers, 2011 to 2017). An adenocarcinoma characterized by the presence of malignant glandular epithelial cells resembling endometrial cells. "There was an association between CLDN7+ staining and low tumor grade and endometrioid adenocarcinoma subtype (p < 0.001 and 0.001 respectively)." (PMID 22272721, 2012). "Previously, we found an over-expression of MSN and under-expression of CLDN7 at the mRNA level in uterine serous carcinoma in comparison to uterine endometrioid adenocarcinoma." (PMID 22272721, 2012). "A total of 95 ovarian tissue samples (7 normal ovarian tissues, 65 serous carcinomas, 11 clear cell carcinomas, 8 endometrioid carcinomas and 4 mucinous carcinomas) were studied for claudin-7 expression." (PMID 21789222, 2011).
esophageal cancer (3 papers, 2013 to 2024). A primary or metastatic malignant neoplasm involving the esophagus. "The study of Usami in esophageal cancer also shows that expression of claudin-7 at the invasive front is statistically correlated with the depth of invasion, stage, lymphatic vessel invasion, and lymph node metastasis." (PMID 27398181, 2016). "Consistent with the disruption of TJs during tumorigenesis, certain claudins including claudin-1 and claudin-7 are downregulated in invasive breast, prostate, and esophageal cancers." (PMID 24009024, 2013). "Claudin-7 was reduced in LUAD, whereas claudin-3 and claudin-4 were increased in esophageal cancer." (PMID 38841188, 2024).
gastric adenocarcinoma (3 papers, 2013 to 2020). "In contrary, increased expression of claudin 7 has been also reported in gastric adenocarcinomas invasive carcinoma of the uterine cervix." (PMID 27398181, 2016). "The overexpression of claudin-6, claudin-7, or claudin-9 enhanced the invasive potential of a gastric adenocarcinoma cell line." (PMID 24073219, 2013).
invasive breast carcinoma (3 papers, 2013 to 2019). A carcinoma that infiltrates the breast parenchyma. "A recent study further supported the poor prognostic significance of claudin-7 expression in ductal invasive breast cancer by showing that claudin-7 expression is associated with a shorter time to recurrence." (PMID 24009024, 2013). "Down-regulation of claudin-7 has been found in invasive breast cancer." (PMID 24245968, 2013). "In contrast, strong membranous or both membranous and cytoplasmic reactivity for Claudin-7 is the representative staining in CHRCC, similar to the expression of Her-2 with a score of 3+ in mammary invasive carcinoma." (PMID 31737127, 2019).
non-small cell lung carcinoma (3 papers, 2013 to 2017). A group of at least three distinct histological types of lung cancer, including non-small cell squamous cell carcinoma, adenocarcinoma, and large cell carcinoma. "In non-small cell lung cancer, survival is significantly poorer in patients with low claudin-7 expression than in those with high claudin-7 expression." (PMID 24009024, 2013). "Non-small cell lung cancer (NSCLC) cell lines sensitive to gefitinib express EMT markers such as E-cadherin, claudin-4 and claudin-7, but resistant cell lines have lost expression of these genes, while the mesenchymal marker vimentin was highly expressed in the resistant cell lines." (PMID 27757846, 2017).
oral squamous cell carcinoma (3 papers, 2013 to 2022). "No study, to the best of our knowledge shows the association of claudin-5, claudin-7 together with occludin expression in oral squamous cell carcinoma (OSCC) and their clinic-pathological prognostic factors." (PMID 27398181, 2016). "The objective of this study was to investigate the expression of claudin-5, claudin-7 and occludin in oral squamous cell carcinoma (OSCC) and their relationships with the prognostically-related clinico-pathologic features." (PMID 27398181, 2016).
thyroid cancer (3 papers, 2006 to 2020). "This is the first report that demonstrates the association of carcinoma-specific complexes comprised of EpCAM with the variant isoforms of CD44 and claudin-7 in thyroid cancer including anaplastic thyroid cancer." (PMID 24727741, 2014). "The involvement of EpCAM, CD44v6 and claudin-7 in the thyroid cancer progression has been showed." (PMID 32091301, 2020). "EpCAM is known to interact with claudin-7 and CD44v6 and plays an important role in tumor progression, and therefore, we tested whether both EpCAM and claudin-7 were expressed in the thyroid cancer cell lines." (PMID 24727741, 2014). "CLDN7 was elevated in cancers of the thyroid, lung, stomach, pancreas, liver, kidney, and ovary." (PMID 16836752, 2006). "Although several studies demonstrated the association of aggressiveness of thyroid cancer and localization of EpCAM, the involvement of EpCAM in carcinoma-specific complexes with variant isoforms of CD44 and claudin-7 has not been studied in thyroid cancer." (PMID 24727741, 2014).
triple-negative breast carcinoma (3 papers, 2024 to 2025). An invasive breast carcinoma which is negative for expression of estrogen receptor (ER), progesterone receptor (PR), and human epidermal growth factor receptor 2 (HER2). "Han Wang and his colleagues conducted a study showing that highly expressed CLDN7 exosomes promote migration and invasion in triple-negative breast cancer (TNBC) cells and serve as prognostic biomarkers for the TNBC." (PMID 40444049, 2025). "Genomic studies have uncovered a claudin-low subtype of triple-negative breast cancer (TNBC), characterized by reduced expression of CLDN3 (claudin 3), CLDN4 (claudin 4), CLDN7 (claudin 7), and E-cadherin." (PMID 39858010, 2025). "In triple negative breast carcinomas (TNBC) high cytoplasmic but not membranous claudin-3 and claudin-7 expression is predictive of poor outcome according to a study group, while another group has shown that membranous claudin-3 overexpression is associated with poor survival in TNBCs." (PMID 39687048, 2024).
viral infection (3 papers, 2005 to 2021). "In this study, we isolated and purified CD cells from CLDN7+/+ and CLDN7−/− mouse kidneys using Dolichos biflorus lectin-coated Dynabeads, and immortalized these cells into cell lines by Lenti-SV40 virus infection." (PMID 31382627, 2019). "Downregulation of CLDN7 reduced viral RNA yield, viral protein production, and release of infectious viral particles in several endothelial cell types, but not in epithelial cells, indicating that CLDN7 implication in viral infection is cell-type specific." (PMID 34616388, 2021). "Our results also demonstrated that virus generated from CLDN-7-transfected 293T cells has two- to 100-fold higher levels of infectivity, suggesting that the presence of CLDN-7 or other types of cellular membrane proteins on the viral envelope is important for viral infection." (PMID 16368003, 2005).
ZIKV infection (3 papers, 2019 to 2022). "In conclusion, we have found that CLDN7 is a susceptibility factor to ZIKV infection in endothelial cells." (PMID 34616388, 2021). "We demonstrate that susceptibility of BBB endothelial cells to ZIKV infection is modulated by the expression of tight-junction protein claudin-7 (CLDN7)." (PMID 34616388, 2021). "Herein, we studied the susceptibility of BBB endothelial cells to ZIKV infection and identified CLDN7 as a key proviral factor in endothelial cells." (PMID 34616388, 2021). "This demonstrates that CLDN7 is specifically involved in hCMEC/D3 susceptibility to ZIKV infection." (PMID 34616388, 2021). "Intriguingly, none of the peptides corresponding to extracellular domains of claudin-7 had a significant impact on ZIKV infection of hCMEC/D3 cells." (PMID 36040168, 2022). "We tested the capacity of the remaining peptides to inhibit ZIKV infection in hCMEC/D3 cells, a human cerebral microvascular endothelial cell line, in which claudin-7 favors ZIKV replication." (PMID 36040168, 2022). "Together, our data suggest that CLDN7 facilitates ZIKV infection in endothelial cells at a post-internalization stage and prior to RNA production." (PMID 34616388, 2021). "Together these data demonstrate that CLDN7 expression favors ZIKV infection in hCMEC/D3 cells." (PMID 34616388, 2021). "We examined whether CLDN7 was also favoring ZIKV infection in two other endothelial cell lines: bone marrow endothelial cells (TrHBMEC) and umbilical vein endothelial cells (HUVEC)." (PMID 34616388, 2021). "In this study, we identified two peptides derived from the N-terminal sequences of claudin-7 and claudin-1, named CL7.1 and CL1.1, respectively, that inhibited ZIKV infection in a panel of human cell lines." (PMID 36040168, 2022). "Nevertheless, we found that the peptide corresponding to the N-terminal 18-mer of claudin-7, named CL7.1, inhibits ZIKV infection in five human cell lines." (PMID 36040168, 2022). "Consequently, we wondered whether targeting the interactions between claudin-7 and ZIKV could be used as a strategy to reduce ZIKV infection in human cells." (PMID 36040168, 2022). "Treatment with the other claudin-7-derived peptides had no significant impact on ZIKV infection." (PMID 36040168, 2022).
allergic rhinitis (2 papers, 2021 to 2023). Inflammation of the nasal mucous membranes caused by an IgE-mediated response to external allergens. "This study assessed the mRNA expression levels of various tight junctions, including occludin (OCLN), claudin-3 and −7 (CLDN3 and CLDN7), desmoglein 3 (DSG3), and thymic stromal lymphopoietin (TSLP) in 30 individuals with Allergic Rhinitis (AR) and 30 non-allergic controls." (PMID 37692890, 2023).
anaplastic thyroid carcinoma (2 papers, 2014 to 2020). "In the present study, we demonstrated that EpCAM, together with CD44 and claudin-7, is associated with the phenotype of anaplastic thyroid cancer both in the established cell lines and clinical specimens." (PMID 24727741, 2014). "Although direct interaction of EpCAM, CD44 variants, and claudin-7 was not examined in our study, the results suggest that complexes of EpCAM with CD44 variants and claudin-7 may be associated with the aggressive phenotype of anaplastic thyroid cancer." (PMID 24727741, 2014). "With regard to claudin-7, its expression was significantly higher in the anaplastic thyroid cancer cell lines, which showed a higher EpCAM expression as well." (PMID 24727741, 2014). "However, to the best of our knowledge, the association of EpCAM, CD44v6 and claudin-7 have not been evaluated in anaplastic thyroid carcinoma." (PMID 24727741, 2014). "In conclusion, our study suggests the possibility that EpCAM, together with CD44v6 and claudin-7 as well as ALDH1, may be involved in the development of the aggressive phenotype of anaplastic thyroid carcinoma." (PMID 24727741, 2014). "Our study suggests the possibility that EpCAM, together with CD44v6 and claudin-7 as well as ALDH1, may be involved in the development of the aggressive phenotype of anaplastic thyroid carcinoma." (PMID 24727741, 2014).
Bladder cancer (2 papers, 2014 to 2026). "We chose five candidate genes (PTPRF, MMP2, VEGFA, CDH1 and CLDN7) that were detected differential expression by Cuffdiff and involved in Bladder cancer pathway, cell adhesion molecules (CAMs) pathway and focal adhesion pathway." (PMID 24622401, 2014).
carcinoma of the endometrium (2 papers, 2012 to 2018).
cervical cancer (2 papers, 2016 to 2019). A primary or metastatic malignant neoplasm involving the cervix. "In contrast to HPV-negative HNSC samples, HPV-positive tumors showed the same tendency as cervical cancers with respect to the expression of COL5A, MMP2, CLDN7, TAGLN, and AURKB, supporting their possible contribution to virus-induced carcinogenesis." (PMID 30918060, 2019).
endometriosis (2 papers, 2020 to 2022). The growth of functional endometrial tissue in anatomic sites outside the uterine body. "Downregulation of claudin-3, claudin-4, and claudin-7 may contribute to the establishment of endometriosis." (PMID 36091010, 2022). "However, as recently published by us, claudin-7 is not downregulated in endometriosis in contrast to subtle changes in localization of claudin-11." (PMID 32140805, 2020). "Recently, we showed no decrease in claudin-7 and only subtle changes in the localization of claudin-11 in ectopic endometrium and suggested that only a partial EMT might be involved in the pathogenesis of endometriosis." (PMID 32140805, 2020).
gastric tumor (2 papers, 2019 to 2022). "When analyzed with the expression changes, the upstream regulators associated with these genes and that were predicted to be inhibited in the gastric tumors included the transcription regulators MYC and NFκB, the Pkc kinases and MAPK8 (JNK) as well as CLDN7." (PMID 31584998, 2019).
head and neck squamous cell carcinoma (2 papers, 2015 to 2019). A squamous cell carcinoma that arises from any of the following anatomic sites: lip and oral cavity, nasal cavity, paranasal sinuses, pharynx, larynx, and salivary glands. "Here, the same tendency in expression changes of TGM2, MMP2, CLDN7, HOXB7, and LCP1 can be found in different cancer types, including cervical and head and neck squamous cell carcinoma." (PMID 30918060, 2019).
lung squamous cell carcinoma (2 papers, 2011 to 2025). "The expression of Claudin-7 was negatively correlated with the expression of Slug in lung squamous cell carcinoma and adenocarcinoma (r=-0.566, 8)." (PMID 21645451, 2011). "The aim of this study is to investigate the expression of Claudin-7, Slug and their correltion with clinicopathological characteristics in lung squamous cell carcinoma and adenocarcinoma." (PMID 21645451, 2011). "The down-regulation of Claudin-7 and overexpression of Slug might be one of pertinent biological markers for malignant transformation and metastasis of lung squamous cell carcinoma and adenocarcinoma." (PMID 21645451, 2011).